MAP3K4 (mitogen-activated protein kinase kinase kinase 4)
Diseases named in the same sentence as MAP3K4 in open-access papers (continued):
Sharing a sentence is not in itself a finding about the gene and the disease.
tumor (17 papers, 2012 to 2025). "Larger tumor size, vascular invasion, intrahepatic spreading, and lymph node metastasis, all indicators of a poor prognosis and recurrence of tumor were substantially associated with low expression of MAP3K4." (PMID 38568424, 2024). "Genome-wide sequencing shows that MAP3K4 and its mutations also frequently appear in several kinds of tumor tissues, such as serous endometrial tumor, wilms tumor, EBV-positive gastric tumor, pancreatic cancer, and family lung cancer." (PMID 38568424, 2024). "Similar to other components within the MAPK pathway, MAP3K4 functions as both a tumor promotor and suppressor, accelerating or decelerating tumor proliferation and metastasis." (PMID 38568424, 2024). "The MAP3K4–p38 MAPK signal cascade pathway plays an important role in tumor invasion and metastasis." (PMID 37313461, 2023). "However, the challenge of effectively targeting MAP3K4 to thwart tumor genetic activation and achieve therapeutic success remains a significant hurdle that demands more in-depth investigation." (PMID 38568424, 2024). "Under hypoxic conditions, we found that exosomal mir-199a-3p may promote tumor invasion and migration by regulating the expression of its downstream molecule MAP3K4 by bioinformatics analysis, firefly and renilla luciferases, western blotting." (PMID 37497404, 2023). "Depending on the context, MAP3K4 is either a proto-oncogene or a tumor suppressor." (PMID 36108089, 2022). "Thirteen kinases differentially expressed at the protein level in GAC tumor tissues with lymph node metastasis were plotted in a heatmap, including known drug targets JAK1, MAP3K4, and PRKCB, among others." (PMID 36520032, 2023). "Only 3 genes (APOA1, MAP3K4 and MMP14) were confirmed to be downregulated in radiosensitive tumours in the preoperative setting." (PMID 30285791, 2018). "Similarly, MAP3K4 has been shown to regulate epithelial-mesenchymal transition (EMT) and metastasis in GC, highlighting its significance in tumor progression and aggressiveness." (PMID 39901302, 2025). "While medicines based on MAP3K4 inhibition- effectively halt tumor growth, it should be noted that they may also make it easier for malignancies to occur in other tissues exposed to oncogenic triggers." (PMID 38568424, 2024). "Differential gene expression between responders (NR = 30) and non-responders (NNR = 12) was observed for APOA1, MAP3K4 and MMP14 genes with over 2-fold downregulation in pRT-responsive tumours." (PMID 30285791, 2018).
infection (3 papers, 2015 to 2022). The state of being infected such as from the introduction of a foreign agent such as serum, vaccine, antigenic substance or organism. "Pattern "Virulent" includes 14 genes whose expression levels were not changed after infection with heat-inactivated MTB H37Rv or the attenuated vaccine strain BCG (e.g. MAP3K4, SEMA4G, BTG1), and only one of these also belongs to the pattern "Virulent" at 18 hours post-infection." (PMID 26586179, 2015).
MAP3K4 also shares sentences with these, for which no sentence is quoted: bacterial infection (2 papers); neuroblastoma (2); non-alcoholic fatty liver disease (2); prostate carcinoma (2); retinoblastoma (2); sarcoma (2); acute myeloid leukemia (1); Alzheimer disease (1); atherosclerosis (1); bladder cancer (1); cardiac arrhythmia (1); colon cancer (1); degenerative diseases (1); Frasier syndrome (1); glomerulopathies (1); hypertrophic cardiomyopathy (1); Infertility (1); Insulin resistance (1); invasive breast carcinoma (1); leukemia (1); lung carcinoma (1); lymph node metastasis (1); malaria (1); muscle atrophy (1); ovarian carcinoma (1); pancreatic cancer (1); prostate adenocarcinoma (1); renal diseases (1); small cell lung carcinoma (1); triple-negative breast carcinoma (1).
A further 2 diseases each share a sentence with MAP3K4 in 1 paper.